DDX5 (DEAD-box helicase 5)
Diseases named in the same sentence as DDX5 in open-access papers (continued):
Sharing a sentence is not in itself a finding about the gene and the disease.
cancer (continued). "Essentially, the dysregulation of DDX5 in various cancer types substantiates its role in facilitating cancer cell proliferation, even though it might assume tumor suppressor functions in specific contexts." (PMID 38136426, 2023). "Moreover, the abnormal expression of DDX5 appears in various cancer cells, such as breast cancers, colon cancers, prostate cancer, lung cancer, gastric cancer, and leukemia." (PMID 36894019, 2023). "This in turn suggests that the DDX5 gene amplification in cancers could occur to compensate for the repressive effect of hypoxia on DDX5." (PMID 37013907, 2023). "This is because all cancer patients have their immune system intact and targeting DDX5 for the treatment of cancer could eliminate the DDX5-mediated immune suppression in patients to further help eliminate tumors." (PMID 37596619, 2023). "Here, we focus on DDX5 and its role in genome stability surveillance and DNA repair in more detail from a cancer therapeutic point of view and with an attempt to unify the seemingly contradictory observation of the oncogenic versus oncosuppressive functions of DDX5." (PMID 37596619, 2023). "Additionally, it is known that DDX5 is a multifunctional target and biomarker, and plays an important role in promoting cancer initiation, progression, metastasis and treatment resistance." (PMID 37596619, 2023). "Thus, this study provides an example that DDX5 can be involved in immune suppression and cancer progression by directly promoting the production of immune cell suppressing cytokines and then attracting neutrophils into TME." (PMID 37596619, 2023). "In summary, DDX5 emerges as an ideal target for the treatment of cancer." (PMID 37596619, 2023). "Thus, DDX5 provides a potential therapeutic target for intestinal inflammatory diseases and the treatment of cancers." (PMID 37596619, 2023). "Our goal is to provide a unifying interpretation to the observations from PDAC and/or HCC in some publications reviewed recently that are inconsistent with others for DDX5 to act as a cancer biomarker and target by using the gradually established DDX5’s DNA repair function." (PMID 37596619, 2023). "Overall, the relevant publications reviewed above suggest that DDX5 could be an ideal cancer therapeutic target to conquer cancer." (PMID 37596619, 2023). "However, this seemingly paradoxical function of DDX5 provides the ideal situation when targeting DDX5 for cancer therapeutics as it provides the ability to potentially avoid adverse side effects on physiology and normal tissues while causing cancer cell death." (PMID 37596619, 2023). "This would provide a novel opportunity for targeting DDX5 to disrupt cancer metabolism." (PMID 37596619, 2023). "DDX5 enhanced cancer cell proliferation and survival as well as metastasis in CRC." (PMID 38023215, 2023). "Together, these observations suggest that targeting DDX5 could potentially shift cancer cells from a growth-arrested state (necessary for DNA repair) to apoptosis and cell killing." (PMID 37596619, 2023). "DDX5 is emerging as an attractive target for cancer therapeutic development." (PMID 37596619, 2023). "Thus, pharmacological inhibition or degradation of DDX5 would also block the abnormal reprogramming of glucose (Warburg effect), lipid and nucleotide metabolisms in cancer to induce apoptosis and cancer cell killing." (PMID 37596619, 2023). "When DDX5 and DDX17 expression is abnormal in the physical examination, it indicates that the patient’s health status is poor, with increased the risk of DDX5-/DDX17-associated cancer." (PMID 35992805, 2022). "We propose that DDX5 has important roles in tumor immunity and the diagnosis of cancer." (PMID 36313454, 2022).
cancer (continued). "First, DDX5/DDX17 can be used as biomarkers for predicting cancer." (PMID 35992805, 2022). "Previous studies have additionally demonstrated that DDX5 is involved in a variety of clinical diseases, especially carcinogenesis and the development of cancer." (PMID 36313454, 2022). "Thus, lncRNAs are involved in the progression of various cancers by regulating the stability of DDX5 or DDX17 at the RNA level and at the protein level or by acting as scaffolding elements in the complex." (PMID 35992805, 2022). "However, by comparing the known roles of the identified interactors with those of DDX3X and DDX5 in the same cancer types, some observations can be made." (PMID 35954483, 2022). "Therefore, DDX5/DDX17 can be used as clinical biomarkers for a cancer diagnosis and for prognosis prediction." (PMID 35992805, 2022). "When DDX5/DDX17 expression is disrupted, the body is at great risk of developing cancer." (PMID 35992805, 2022). "DDX5 can regulate cancer development by affecting cell autophagy." (PMID 35992805, 2022). "Meanwhile, we can also take time to further study the MOA for FL118‐DDX5 interaction and signalling regulation as well as in each of DDX5's downstream targets and their associated signalling network during the development of FL118 into clinical application for cancer treatment." (PMID 35604033, 2022). "Therefore, the expression of DDX5 protein was determined in nine cancer types using the CPTAC dataset." (PMID 36313454, 2022). "While this observation is consistent with the fact that cancer cells are heterogeneous, this clearly indicates that the DDX5 target may have differing degrees of importance to different PDAC cells." (PMID 35604033, 2022). "Both DDX3X and DDX5 interact with hundreds of different cellular proteins, and depending on the specific pathways in which they are involved, both proteins can either act as suppressors of cancer or as oncogenes." (PMID 35954483, 2022). "However, in esophageal squamous cell carcinoma, DDX5 increases endoplasmic reticulum stress and reduces autophagic flux to promote cancer proliferation and metastasis." (PMID 35992805, 2022). "DDX5 supports the energy supply in cancer cells by promoting respiratory function." (PMID 35992805, 2022). "DDX3X and DDX5 may thus be considered important nodes in the cancer pathosome, whose functions can be influenced by their interacting partners." (PMID 35954483, 2022). "The roles of DDX5 in different cancer types are detailed in the next sections." (PMID 35954483, 2022). "Thus, DDX5 is considered an upstream master regulator in cancer, with great potential to become a critical target and biomarker for cancer precision medicine." (PMID 35604033, 2022). "DDX3X and DDX5 are correlated with tumorigenesis in several cancers." (PMID 33608512, 2021). "It is reported that DDX5 plays tumor-promoter role in various cancers." (PMID 34234865, 2021). "In cancer cells, Thrap3 interacts with DEAD-box helicase 5 (DDX5) and localizes to R-loops." (PMID 34697388, 2021). "It is believed that DDX5 expression is upregulated in multiple cancer types." (PMID 33807895, 2021). "DDX5 plays a proliferative or oncogenic role in cancer through the coactivation of Androgen Receptor (AR), Runx2 and the p50 subunit of NF-κB, and upregulation of cyclin D1 and c-Myc consistent with β-catenin activation as well as genes necessary for DNA replication." (PMID 33804185, 2021). "DDX5 and eEF1A2 are two oncogenes in several cancer types according to previous researches 25-27." (PMID 33859743, 2021). "DDX5 also played important roles in promoting cancer cell proliferation and metastasis." (PMID 32694946, 2020).
cancer (continued). "Otherwise, studies showed that downregulation of DDX5 in gastric and lung cell lines abrogates proliferation, which suggested that DDX5 could affect cancer cell proliferation." (PMID 32690860, 2020). "The staining of DDX5 was mostly localized to the nucleus of cancer cells." (PMID 32694946, 2020). "The results also showed that the levels of O‐GlcNAcylation and DDX5 were significantly increased in cancer tissues, and it was found to be positively correlated by the expression analysis of O‐GlcNAcylation and DDX5 in cancer tissues." (PMID 30484950, 2019). "DDX5 promoted cancer cell viability via direct regulation of NF-кB p50." (PMID 29535419, 2018). "Moreover, most identified helicases, including DHX9 and DDX5, showed mRNA overexpression in a range of cancers, based on the ONCOMINE database." (PMID 29742442, 2018). "Many reports identified DDX5 as transcriptional co-regulator to promote cancer cell proliferation." (PMID 28216662, 2017). "Moreover, our results showed that knockdown of DDX5 could partially reverse the effects of circASCC3 overexpression on cancer cell growth and apoptosis." (PMID 40067902, 2025). "Thus, targeting DDX5 could potentially shift cancer cells from a growth-arrested state (necessary for DNA repair) to apoptosis and cell killing." (PMID 37596619, 2023). "Notably, the coupled increase of YTHDC1 and DDX5 expression in a larger set of human cancers suggests that both factors might be relevant for the biogenesis of specific subsets of circRNAs in tumors other than RMS." (PMID 37019933, 2023). "Ample research findings in recent decades have shown that DDX5 could form a complex with β-catenin protein, which stimulated β-catenin transcriptional capacity and thus triggered the transcription of downstream target genes in human cancers." (PMID 38040691, 2023). "Therefore, DDX5 is a promising drug target for cancer diagnosis." (PMID 36894019, 2023). "Thus, targeting DDX5 instead of targeting its individual partners may be a particularly efficient way that is equivalent to target all partnering proteins in cancer therapy." (PMID 37596619, 2023). "Targeting DDX5 may not only produce little toxicity to normal tissues but the pharmaceutical inhibition or degradation of DDX5 may also produce positive effects against DDX5-induced inflammation thus benefiting the overall health of cancer patients." (PMID 37596619, 2023). "Importantly, DDX5 uses distinct signaling cascades by interacting with different proteins in different tissues/cells as well as in normal tissues/cells versus in cancer tissues/cells to elicit distinct roles in healthy versus in cancer cells." (PMID 37596619, 2023). "Moreover, many anticancer drugs inhibit cancer by affecting DDX5/DDX17 activity." (PMID 35992805, 2022). "Thus, the interaction of ANLN with DDX5 might be an additional component of this pathway and could explain the oncosuppressive role of DDX5 in this type of cancer." (PMID 35954483, 2022). "Understanding the interplay of the different cellular contexts, as defined by the molecular interaction networks of DDX3X and DDX5 in different tumors, with the cancer-specific roles played by these proteins could help to explain their apparently conflicting roles as cancer drivers or suppressors." (PMID 35954483, 2022). "Thus, the oncogenic role of SRSF1 and DDX5 might also be to increase the DNA damage tolerance of cancer cells by reducing R-loop accumulation and preventing cell death." (PMID 35954483, 2022). "In another study, DDX5 was found to interact with SUZ12, the core subunit of the chromatin-modifying PRC2 complex, and, in association with the lncRNA HOTAIR, to repress transcription of the cancer stem cell marker EpCAM, as well as that of stemness-related genes Nanog, Oct4 and Sox2." (PMID 35954483, 2022).
cancer (continued). "There are several studies that focus on specific inhibitors or drugs of the host DEAD-box helicase to inhibit virus replication or treat cancers, but it remains to be determined whether small molecular inhibitors of the interaction between DDX5 and Rev can be found." (PMID 29642538, 2018). "In this review, we highlight recent discoveries that position DDX5 as a promising therapeutic target in RMS, focusing on its oncogenic functions and its contribution to tumorigenesis and cancer progression." (PMID 40950397, 2025). "The analysis revealed that the DDX5 mRNA increase in tumors is related to decreased overall survival (OS), progression-free interval (PFI), and disease-specific survival (DSS) in 3 cancers but increased OS, PFI, and DSS in others." (PMID 37596619, 2023). "Many of these pathways are involved in different types of cancer, and DDX3X and DDX5 play a major role in their regulation." (PMID 35954483, 2022). "Together, these observations further support the findings that DDX5 is the direct biochemical target of FL118 and is a master regulator of cancer cell and tumour survival and growth." (PMID 35604033, 2022). "In addition, we present a list of interacting proteins and discuss the possible contribution of some of these protein–protein interactions in determining the roles of DDX3X and DDX5 in the process of cancer proliferation, also suggesting novel hypotheses for future studies." (PMID 35954483, 2022). "In this study, we report that FL118 binds to and inhibits both the phosphorylation and expression of DDX5 (p68) in CRC and PDAC cancer cells." (PMID 35604033, 2022). "In conclusion, we believe that the analysis presented here supports the roles of DDX3X and DDX5 as important nodes in the cancer pathosome and might suggest new venues of research for a better understanding of their roles in tumor transformation and cancer progression." (PMID 35954483, 2022). "Second, DDX5 and DDX17 can be used as clinical predictive molecules for predicting cancer recurrence and prognosis." (PMID 35992805, 2022). "Third, regulating the posttranslational modification of DDX5/DDX17 can change their functions and targets, improving the tumor response to anticancer drugs and reducing the drug resistance of malignant tumors." (PMID 35992805, 2022). "Overexpression of miR-195-5p abated the cancer-promoting function of TUG1 and curbed the profile of the HDGF/DDX5/β-catenin axis." (PMID 35014946, 2022). "Among them, we want to highlight DDX3 as a confirmed target for cancer and antiviral therapy, while others, like DDX46, DHX9 and DDX5, are still poorly studied in this context." (PMID 33804185, 2021). "For the case of fibroblast cells associated dataset, the most significant pathway obtained was Proteoglycans in cancer (p value 1.2 × 10−3) (CD63, DDX5, DCN, LUM, ITGB1)." (PMID 34071236, 2021). "We identified a novel cancer driver lncRNA, PRADX that recruits PRC2/DDX5 complex by interacting with EZH2 and promotes NF-κB activity via UBXN1 suppression, which in turn contributes to GBM and COAD tumorigenesis." (PMID 33754075, 2021). "DDX5 is a multi-functional RNA DEAD-box helicase, which greatly contributes to cancer development and plays roles in tumorigenesis, proliferation, differentiation, metastasis, and malignancies." (PMID 33909701, 2021). "Seven target genes, namely DDX5, SOS2, ACTG1, EZR, FN1, HCLS1 and PIK3R5, were involved in proteoglycans in cancer signaling pathway." (PMID 32293320, 2020). "Transcription factors such as HMBOX1, DDX5, and ZBTB5, which were identified to be co-regulated by miR-20a and miR-15b, have implication on cancer progression." (PMID 31602261, 2019).
cancer (continued). "Some of the switch factors controlling macroH2A1 splicing into macroH2A1.1 or macroH2A1.2 isoforms have been identified in cancer cells: QKI and RNA helicases Ddx17/Ddx5." (PMID 27800025, 2016). "According to these reports, despite the lack of detailed molecular mechanisms, the importance of DDX5 in cancer development and malignant transformation has been demonstrated by many researchers." (PMID 38612503, 2024). "Other family members such as DDX51, DDX5, and DDX53 play important roles in several cancers." (PMID 38807916, 2024). "In this review, we focus on DDX5, which is known to be a major member in the DEAD-box RH family, plays diverse roles in human cancer, and potentially represents a prime target for cancer therapeutics." (PMID 37596619, 2023). "Together, our data highlight the significant energy‐consuming processes a hypoxic cell employs to turn off the expression of specific genes such as DDX5 and, not surprisingly, that cancers circumvent this biological response." (PMID 37013907, 2023). "However, in most cancers, ARF expression is significantly decreased, then a significant increase in nucleolar DDX5 expression has been observed." (PMID 35992805, 2022). "Dead-box Helicase 5 (DDX5), a member of DEAD Box family of RNA helicase, is involved in many physiological processes such as RNA metabolism, cell proliferation, apoptosis, and has also been found to be highly expressed in malignant tumor tissues." (PMID 35634318, 2022). "DDX5 and DDX17 are abnormally expressed in many tumors and participate in tumorigenesis, tumor cell proliferation, invasion and metastasis, which exert a profound impact on cancer development." (PMID 35992805, 2022). "The expression of DDX5 mRNA in 33 cancer types was compared to that of matched normal tissues based on the data retrieved from TCGA." (PMID 36313454, 2022). "The enhanced expression of DDX5 mRNA in the tumor samples was related to decreased overall survival (OS), progression-free interval (PFI), and disease-specific survival (DSS) in three cancers, but increased OS, PFI, and DSS in other cancers." (PMID 36313454, 2022). "Since it was already shown that the oncogenic effect of high DDX5 levels also involves the deregulation of NOTCH1 and E2F pathways, it should be interesting to study the functional significance of the interaction of DDX5 with HEY1 in this type of cancer." (PMID 35954483, 2022). "Together, these studies indicate that DDX5 acts as an upstream master regulator to control the expression of survivin, Mcl‐1, XIAP, cIAP2, c‐Myc and mKras, which are key oncogenic proteins involved in cancer development and malignant networks." (PMID 35604033, 2022). "Suppression of DDX5 or CCM1 changed the expression levels of SLUG and TWIST, but not SNAIL, although all three are generally considered important transcription factors involved in EMT in cancer cells." (PMID 33807895, 2021). "Other interesting examples included AGO4, LIN28A and SMAD2 overmutated in BLCA (an otherwise extremely low-mutation cancer with no mutations in other genes); LIN28B overmutated in SKCM; PRKRA overmutated in OV; and DDX5 overmutated in BRCA and KIRP." (PMID 33406242, 2021). "DDX5 and related DDX17 (p72) are involved in a variety of cellular processes, including transcription, pre-mRNA and rRNA processing, alternative splicing and miRNA processing, and they are also deregulated in a range of cancers." (PMID 33804185, 2021).